SLFN14 (schlafen family member 14)
Description:
[Protein SLFN14]: Shows no ribosome-associated and endoribonuclease activities. [C-terminally truncated SLFN14 endoribonuclease]: Displays polysome-associated endoribonuclease activity towards mRNAs and rRNAs. May play a role in RNA surveillance pathways by recognizing stalled ribosomes and triggering endonucleolytic cleavage of aberrant mRNAs (Probable). Cleaves different types of rRNAs and mRNAs in a magnesium- and manganese-dependent and ATP-independent manner (By similarity). Involved in correct maturation of megakaryocytes and especially important for proplatelet extension.
Synonyms: BDPLT20
Tractability: PROTAC: ubiquitination databases record sites on it.
Gene: Protein-coding gene on chromosome 17 (35,543,985 to 35,560,819, reverse strand). Ensembl gene ENSG00000236320.
Subcellular location: Nucleus (Protein SLFN14)
Gene Ontology:
Molecular function: ribosome binding; RNA endonuclease activity; RNA nuclease activity
Biological process: mRNA catabolic process; platelet maturation; rRNA catabolic process; cellular response to magnesium ion; cellular response to manganese ion
Cellular component: cytoplasm; nucleus
Genetic constraint (gnomAD): Loss-of-function variants: 45 observed, 56.53 expected, observed/expected ratio (o/e) 0.8, 90% interval 0.63 to 1.02. The upper end of that interval is the gene's LOEUF score, 1.02, which puts it in group 4 of 6, group 1 being the genes least tolerant of losing a copy. Missense variants: 954 observed, 1,105.2 expected, observed/expected ratio (o/e) 0.86, 90% interval 0.82 to 0.91. Synonymous variants: 385 observed, 396.73 expected, observed/expected ratio (o/e) 0.97, 90% interval 0.89 to 1.06.
Gene-disease validity (ClinGen):
ClinGen rates the evidence that SLFN14 causes each of these diseases.
platelet-type bleeding disorder 20 (autosomal dominant): Moderate.
Homologues: Orthologues: chimpanzee SLFN14 (99% identical), macaque SLFN14 (95% identical), dog SLFN14 (78% identical), pig SLFN14 (78% identical), rabbit SLFN14 (77% identical), mouse Slfn14 (70% identical), rat AC118772.1 (68% identical). Paralogues in human: SLFN11 (43% identical), SLFN13 (43% identical), SLFN5 (41% identical), SLFN12 (27% identical), SLFN12L (26% identical), SLFNL1 (8% identical).
Diseases named in the same sentence as SLFN14 in open-access papers:
SLFN14 is named in the same sentence as 19 diseases in open-access papers, as found by Europe PMC text mining. Sharing a sentence is not in itself a finding about the gene and the disease. The quoted sentences say what the papers report.
Thrombocytopenia (11 papers, 2016 to 2026). A reduction in the number of circulating thrombocytes. "To date, five variants (K218E, K219E/N, V220D, and R223W) of SLFN14 related to thrombocytopenia have been reported, all focusing on the hotspot within the AAA protein domain." (PMID 40510593, 2025). "In conclusion, this case report provides a foundation for further research into the complex relationship between SLFN14 genetic variants and thrombocytopenia." (PMID 40521396, 2025). "All previously reported cases of SLFN14 genetic variant‐associated thrombocytopenia were heterozygous and exhibited macrothrombocytopenia, with platelet counts below 150 × 109/L, suggesting this as a characteristic feature of SLFN14‐related thrombocytopenia." (PMID 40521396, 2025). "In this study, we have identified a novel case of severe thrombocytopenia stemming from a genetic variant in the helicase domain of the SLFN14 gene." (PMID 40521396, 2025). "Previous reports of SLFN14‐associated thrombocytopenia were predominantly limited to genetic variants within the N‐terminal AAA domain." (PMID 40521396, 2025). "This study identifies a novel SLFN14 T853fs mutation in the helicase domain associated with thrombocytopenia." (PMID 40510593, 2025). "Schlafen 14-related (SLFN14-related) thrombocytopenia is a rare bleeding disorder caused by SLFN14 mutations altering hemostasis in patients with platelet dysfunction." (PMID 40794453, 2025). "The structure uncovers the structural environment of the SLFN14-related thrombocytopenia hotspot mutations, suggesting dysregulation of RNA binding within the C-lobes." (PMID 40592880, 2025). "Unlike some IT cases, which are asymptomatic in platelet quality/funtion, patients with SLFN14 mutations present with moderate thrombocytopenia, a history of severe bleeding, and platelet ATP secretion defects." (PMID 40510593, 2025). "In this study, we identified a novel T853fs mutation in a SLFN14-related inherited thrombocytopenia pedigree." (PMID 40510593, 2025). "SLFN14 is one of the most recently discovered genes linked to inherited thrombocytopenia where several heterozygous missense mutations in SLFN14 were identified to cause defective megakaryocyte maturation and platelet dysfunction." (PMID 29678925, 2018). "However, to date, no clinical cases have been identified in which genetic variants in the C‐terminal helicase domain of SLFN14 are linked to severe thrombocytopenia and hemorrhagic syndrome." (PMID 40521396, 2025). "The relationship between SLFN14 mutation and thrombocytopenia remains unclear." (PMID 40510593, 2025). "However, the exact mechanism through which mutations in SLFN14 mediate thrombocytopenia and aberrant platelet function is unknown." (PMID 27025194, 2016). "The twins exhibited significantly reduced platelet counts, abnormal megakaryocyte accumulation, and arrested maturation, broadening the spectrum of SLFN14‐related thrombocytopenia." (PMID 40521396, 2025). "Our cryoEM structure unveils the SLFN14-related thrombocytopenia hotspot at the entrance of the RNA cleft." (PMID 40592880, 2025). "Unlike AAA-domain mutations, T853fs does not alter mitochondrial translation, but significantly affects ion channel and dense granule pathways crucial to platelet function, highlighting genotype-phenotype diversity in SLFN14-related thrombocytopenia." (PMID 40510593, 2025). "It is noteworthy that previous reports on SLFN14‐related thrombocytopenia have only described genetic variants in the N‐terminal AAA domain, although the SLFN14 heterozygote (c.2557insC) has also been associated with atrial septal defect in a family." (PMID 40521396, 2025). "This emphasizes the complexity of the genotype‐phenotype correlation in SLFN14‐related disorders and suggests that genetic variants in distinct domains may disrupt different functional aspects of the SLFN14 protein, ultimately leading to thrombocytopenia through diverse molecular mechanisms." (PMID 40521396, 2025).
Thrombocytopenia (continued). "All individuals had macrothrombocytopenia, characterized by a reduced platelet count (below 150x109/L) and enlarged platelets suggesting this is a typical feature of SLFN14 related thrombocytopenia." (PMID 31378119, 2020). "To unveil the cellular function of SLFN14 and the link between SLFN14 and thrombocytopenia, we examined SLFN14 (WT/mutants) in in vitro models." (PMID 29678925, 2018). "This positively charged surface at the RNA cleft entrance may facilitate SLFN14 substrate recruitment and could dysregulate target selectivity in SLFN14-related thrombocytopenia patients." (PMID 40592880, 2025). "For this reason, we can hypothesize that SLFN14 contributes to improper platelet formation from the disrupted translation of their precursors, megakaryocytes, which then results in an inherited thrombocytopenia." (PMID 31378119, 2020).
Macrothrombocytopenia (4 papers, 2023 to 2025). "In this context, Meg-01 cells transfected with SLFN14-WT and SLFN14-T853fs were analyzed by RNA sequencing (RNA-seq) to explore the potential pathways involved in Thr853fs-associated inherited macrothrombocytopenia." (PMID 40510593, 2025).
Bleeding disorder (2 papers, 2023 to 2025). "SLFN14 has been associated with the autosomal-dominant “Bleeding disorder, platelet-type, 20 (MIM #616913)”." (PMID 36319675, 2023).
viral infection (2 papers, 2022 to 2024). "Next, we evaluated the effect of SLFN14 on the expression of rare codon-enriched transcripts expressed by viral infection." (PMID 38675845, 2024). "Viral infections induce SLFN14 expression in a manner similar to that of RNase L, and it may participate in the clearance of total cellular RNA to inhibit viral reproduction." (PMID 35216035, 2022).
breast carcinoma (1 paper, 2023). "Publicly available database analysis reveals that SLFN14 is downregulated in breast cancer and has a positive survival correlation to this malignancy." (PMID 38067362, 2023).
Hypercholesterolemia (1 paper, 2013). An increased concentration of cholesterol in the blood. "Of the DEGs in the MCA that were up-regulated in the hypercholesterolemia plus sham group vs. sham controls on a normal diet, SLFN14 had the largest fold change, followed by CA1 and Gap protein alpha-3 protein-like (LOC100357902)." (PMID 23874591, 2013). "Among the highly up-regulated genes in the MCA of the hypercholesterolemia plus sham group compared to sham controls were SLFN14, CA1, and LOC100357902." (PMID 23874591, 2013). "Of the DEGs in the MCA that were up-regulated in the hypertension plus hypercholesterolemia group vs. sham controls on a normal diet, EPHA1 had the largest fold change, followed by SP110, and SLFN14." (PMID 23874591, 2013). "Among the highly up-regulated genes in the MCA of the hypertension plus hypercholesterolemia group compared to sham controls were EPHA1, SP110, SLFN14." (PMID 23874591, 2013).
influenza (1 paper, 2022). An acute viral infection of the respiratory tract, occurring in isolated cases, in epidemics, or in pandemics; it is caused by serologically different strains of viruses (influenzaviruses) designated A, B, and C, has a 3-day incubation period, and usually lasts for 3 to 10 days. "Depletion of SLFN14 limited the upregulation of IP-10, a major ISG, following influenza infection." (PMID 35216035, 2022).
inherited thrombocytopenia (1 paper, 2025). An instance of thrombocytopenia that is inherited. "SLFN14 dysregulation is causative for inherited thrombocytopenia, a collection of disorders typified by low platelet count, excessive bleeding, and ribosome dysfunction." (PMID 40592880, 2025). "SLFN14 dysregulation is linked to human diseases, including ribosomopathies and inherited thrombocytopenia, thus underscoring the importance of establishing the signals coordinating its RNA processing activity." (PMID 40592880, 2025).
malignant melanoma (1 paper, 2021). "Although SLFN11, SLFN12, SLFN13, and SLFN14 are expressed comparably in primary melanocytes and malignant melanoma cells, the high expression of SLFN5 in primary melanocytes is suppressed at both mRNA and protein levels in malignant melanoma cells." (PMID 34571887, 2021).
Platelet—type Bleeding Disorder 20 (1 paper, 2025). "Platelet‐type bleeding disorder 20 (BDPLT20), caused by heterozygous SLFN14 genetic variants, represents an autosomal dominant form of genetic thrombocytopenia." (PMID 40521396, 2025). "Based on these test results, the patient was diagnosed with Platelet—type Bleeding Disorder 20 (BDPLT20), which is caused by heterozygous SLFN14 gene's genetic variants." (PMID 40521396, 2025).
stomach adenocarcinoma (1 paper, 2022). "The findings revealed that SLFN5, SLFN11, SLFN12, SLFN12L, SLFN13, and SLFN14 were expressed at higher levels in many cancers, including GC (stomach adenocarcinoma; STAD), while the SLFN14 expression levels were relatively low in all tumor and normal tissues." (PMID 36090985, 2022).
cancer (3 papers, 2020 to 2022). A tumor composed of atypical neoplastic, often pleomorphic cells that invade other tissues. "SLFN11, SLFN5, SLFN13, and SLFN12 exhibit a wide range of transcription levels in cancer cells, whereas SLFN12L, SLFN14 and SLFNL1 are barely expressed in cancer cell lines." (PMID 35768579, 2022).
infection (1 paper, 2024). The state of being infected such as from the introduction of a foreign agent such as serum, vaccine, antigenic substance or organism. "HEK293T cells were co-transfected with a plasmid encoding a single-round infection HIV-1 expressing eGFP (HIVeGFP) and either an empty plasmid or plasmids expressing mouse or human SLFN14, and SLFN14 was determined by immunostaining and confocal microscopy analysis." (PMID 38675845, 2024).
SLFN14 also shares sentences with these, for which no sentence is quoted: atrial septal defect (1 paper); Diamond-Blackfan anemia (1); HIV-1 infection (1); Hypertension (1); Shwachman-Diamond syndrome (1); tumor (1).